TPH2 (tryptophan hydroxylase 2)
Diseases named in the same sentence as TPH2 in open-access papers (continued):
Sharing a sentence is not in itself a finding about the gene and the disease.
depression (continued). "To confirm the depressive changes induced by CVS and to understand the molecular mechanisms in the brain of rats, we also evaluated two important genes used as molecular indicators of depression: Fkbp5 (FK506 binding protein 5) and Tph2 (tryptophan hydroxylase 2)." (PMID 30533439, 2018). "Etiological classification of depression expressed by peripheral (TPH1, TDO, IDO) and central (TPH2, KMO) enzymes of tryptophan metabolism may enable depression to be viewed as a clear box, with the inner components available for inspection and treatment." (PMID 25540092, 2014). "The described etiological classification expressed by peripheral (TPH1, TDO, IDO) and central (TPH2, KMO) enzymes allows depression to be viewed as a clear box with the inner components, or logic, available for appropriate individualized inspection and treatment." (PMID 25540092, 2014). "Although not shown in the present study, insufficient tph2 or lack of serotonin has been shown to lead to mood disorders such as depression, schizophrenia and neurodegeneration such as Alzheimer’s dementia." (PMID 24416346, 2014). "Collectively, these genes contribute to diverse regulatory pathways, including neurotransmitter metabolism (Tph2), neurotrophic signaling (BDNF), metabolic regulation (Sucnr1), and ribosomal function (Rps26), supporting their multilayered regulatory roles in the development of depression." (PMID 40656047, 2025). "The TPH2-R439H mouse, an analogous mutation to the R441H mutation found in human depressive patients, not only lacked TPH2 but also exhibited increased depression and anxiety-like behaviors, reduced levels of 5-HT and 5-HIAA in the brain, and fewer enteric neuronal 5-HT in the gut." (PMID 39346901, 2024). "In the pain-depression dyad model, we evaluated immobile time, neurotransmitter levels, interleukin-1 (IL-1β) and tumor necrosis factor-α (TNF-α) levels, and the expression of mRNA of brain-derived neurotrophic factor (BDNF) and tryptophan hydroxylase 2 (Tph2)." (PMID 38259687, 2023). "In addition, tryptophan 5-hydroxylase 2 (TPH2), an enzyme involved in serotonin synthesis, was found to have a strong mimicry with the S protein of SARS-CoV-2, potentially contributing to anxiety and depression." (PMID 34776871, 2021). "In the present study, 113 women with diagnosed mild or moderate depression (patients) and 219 women without depression (healthy controls) were genotyped for polymorphisms in six serotonergic candidate genes: HTR2A, HTR1B, HTR2C, TPH1, TPH2, and MAO-A." (PMID 22619623, 2012). "Focusing on the serotonergic system—the foundation of the monoamine hypothesis of depression—we observed a significant reduction in 5-HT levels in the PFC following FMT, along with H3K27me3-mediated transcriptional repression of key genes including Tph2, Htr1d, Htr2a, Htr3a, Htr6, and Htr7." (PMID 41041075, 2025). "However, there was no change in the ERβ/TPH2/5-HT pathway or depression-like behavior in female Ahi1 KO and chronic restraint stressed mice, implying that there may be other signaling pathways involved in the regulation of 5-HT and behavior in female Ahi1 KO and chronic restraint stress mice." (PMID 35643536, 2022).
Anxiety (67 papers, 2008 to 2026). Intense feelings of nervousness, tension, or panic often arise in response to interpersonal stresses. "In rodents, genetic deletion of TPH2 (TPH2-KO) causes increased aggression, social deficits, and altered anxiety-like behaviors." (PMID 39748904, 2024). "TPH2 expression is closely associated with neuropsychiatric symptoms, such as anxiety and depressive-like behavior, as decreased TPH2 expression induces reduced serotonin synthesis." (PMID 39475992, 2024). "For example, two different models of inescapable stress increase tph2 mRNA expression in the cDRD in association with increased anxiety-like defensive behavioral responses." (PMID 38705984, 2024). "All models evaluating the association between SLC6A4/TPH2 methylation and measures of early stress, anxiety or depressive symptoms and including cells proportions showed a significant association between lymphocytes proportions and CpGLV." (PMID 38802956, 2024). "First, no detailed mechanistic explanation is available for the role that TPH2 gene polymorphism plays in the relationship between childhood trauma and anxiety behavior mediated by the GMV of the thalamus subregion." (PMID 38093326, 2023). "Anxiety and risk-taking levels in the dark-light box (DL-box) test were similar between genotypes, although Tph2−/− rats showed high variability in responses." (PMID 36798444, 2023). "This conclusion is supported by evidence from murine models that indicate TPH2 abundance is associated with anxiety-like behaviors and is particularly sensitive to early life perturbations." (PMID 36704012, 2022). "Repetitive CRHR activation in BNST, caused anxiety, increases the genes expression of the serotonergic systemin DR, including Tph2 (a gene of a key serotonin synthesisenzyme) and Slc6a4 (a gene encoding a serotonin transporter(SERT))." (PMID 34901719, 2021). "Reduced Tph2 expression is associated with an impulsivity‐, aggression‐, and anxiety‐related phenotype combined with alterations in prefrontal cortex, anterior cingulate, and amygdala." (PMID 33523602, 2021). "In a different model with an inactivating mutation of TPH2, increased anxiety-like behaviors have been documented." (PMID 30377380, 2019). "Priming the amygdala using the stress-related neuropeptide urocortin 1 resulted not only in increased social anxiety, but was also linked to Tph2 expression changes." (PMID 31133792, 2019). "Inescapable stress causes a region-specific increase of tph2 mRNA and Tph2 protein, and is likely to mediate diverse behavioral consequences, including anxiety-related and depressive-like behavior." (PMID 29520369, 2018). "In comparison, chronic corticosterone treatment also causes anxiety- and depressive-like behavior and has been shown to disrupt the diurnal rhythm of tph2 mRNA expression in the DRD, DRC and DRV." (PMID 29520369, 2018). "Here we investigate the influence of constitutively deficient 5-HT synthesis on stressor-related anxiety-like behaviors using Tryptophan hydroxylase 2 (Tph2) mutant mice." (PMID 28972592, 2017). "A previous study showed that higher levels of TpH2 mRNA in the caudal DRN were associated with less anxiety-like behavior in the OFT; the current study also found this association." (PMID 28008302, 2016). "In addition, we explored the association between SLC6A4 and TPH2 methylation and measures of early life and recent stress, depressive and anxiety symptoms on 297 healthy individuals." (PMID 38802956, 2024). "Based on our findings, we suggest that the TPH2 rs7305115 gene polymorphism might mediate the relationship between childhood trauma and anxiety by regulating the GMV of RPPTha, especially the reduced GMV of G carriers." (PMID 38093326, 2023). "Moreover, the G allele of the TPH2 polymorphism was associated with the occurrence of post-stroke anxiety." (PMID 31817010, 2019).
Anxiety (continued). "In addition, administration of the GSK3 inhibitor 4-benzyl-2-methyl-1,2,4-thiadiazolidine-3,5-dione (TDZD-8) or GSK3β haploinsufficiency rescue enhanced ‘anxiety’ and ‘behavioural despair’ phenotypes in 5-HT-deficient R439H tph2 knockin mice." (PMID 22826345, 2012). "However, it has to be noted that the reduced level of anxiety-related behavior in elevated plus maze, novelty suppressed feeding, and light-dark box displayed by Tph2-/- mice is possibly caused by enhanced impulsivity, as suggested by overall reduced response latencies." (PMID 25901271, 2015). "Estrogen and progesterone increased TPH2 mRNA in the dorsal raphe region of female macaques, and estrogen increased TPH2 in the rat raphe nuclei and ameliorated anxiety-like behavior." (PMID 40243512, 2025). "Our results show animals fed a HFD had higher expression of tph2, htr1a and slc6a4 in the anxiety-related cDRD subregion." (PMID 38705984, 2024). "Before the resident-intruder test, exploratory, anxiety-like and compulsive-like behaviors were evaluated in TPH2-KO rats." (PMID 39748904, 2024). "Here we conducted a nine-week HFD protocol in male rats, followed by an analysis of the gut microbiome diversity and community composition, brainstem serotonergic gene expression (tph2, htr1a, and slc6a4), and anxiety-related defensive behavioral responses." (PMID 38705984, 2024). "Overall, our results show that a HFD increases tph2, htr1a and slc6a4 mRNA gene expression in areas of the DR, including subregions (e.g. cDRD) involved in the regulation of anxiety-related behaviors." (PMID 38705984, 2024). "Higher expression of tph2 in the cDRD is a particularly consistent finding in several chronic anxiety-like states in rodents, and in persons with affective disorders." (PMID 38705984, 2024). "Only when facing the dynamic complexity and uncertainty of naturalistic conditions of choices were Tph2−/− rats unable to adjust their behavior and were revealed as a promising model for studying transdiagnostic markers of ICDs and anxiety." (PMID 36798444, 2023). "Our results demonstrate that childhood trauma interacting with the TPH2 gene has long-term structural effects on brain gray matter volume and anxiety behaviour, and the TPH2 gene polymorphism may play a role in the process of childhood trauma affecting anxiety behaviour mediated by brain GMV." (PMID 38093326, 2023). "A more recent study extended these findings to adult NHPs (11 months), with reduced serotonin levels, an altered TPH2 expression, and increased anxiety-like behaviours persisting despite being weaned onto a regular diet." (PMID 36984895, 2023). "Time to descend in the step-down avoidance anxiety test was also significantly different between these groups (t = 5.708, df = 31, P < 0.0001, unpaired t-test), with Tph2+/− mice showing shorter latency to step down than Tph2+/+ mice." (PMID 37542675, 2023). "In the escape behavior assay, the tail pick-up time was significantly longer in female Tph2+/− mice than in Tph2+/+ mice (t = 5.120, df = 14, p = 0.0002, unpaired t-test), suggesting higher anxiety and impulsivity in the mutants." (PMID 37542675, 2023). "A similar relationship between aggression and anxiety has been described in mice (e.g. tryptophan hydroxylase 2 knockout mice), while studies in other rodents report the opposite phenotype (high aggression and high anxiety;)." (PMID 35501893, 2022). "We show that Tph2–/– rats displayreduced anxiety-like behavior and a high level of aggression in socialinteractions." (PMID 36197033, 2022). "In conclusion, our study demonstratedreduced anxiety but exaggerated aggression in Tph2–/– male rats and reveals for the first time a potential involvementof altered oxytocin system function." (PMID 36197033, 2022). "Participants were genotyped for TPH2 G‐703T and phenotyped according to trait impulsivity, aggression, and anxiety." (PMID 33523602, 2021).
Anxiety (continued). "After demonstrating the time course of 5-HT reduction after Tph2 icKO induction, we investigated anxiety and depressive-like behavior 4–6 weeks after the injections." (PMID 33686115, 2021). "The aim of the study was to examine how TPH2 G‐703T was related to trait impulsivity, aggression, and anxiety (i.e., the reverse Tph2‐/‐ phenotype) in children and adolescent with and without ADHD." (PMID 33523602, 2021). "Donner N., Davies S., Fitz S., Kienzle D., Shekhar A., Lowry C. Crh receptor priming in the bed nucleus of the stria terminalis (BNST) induces tph2 gene expression in the dorsomedial dorsal raphe nucleusand chronic anxiety." (PMID 34901719, 2021). "Immunofluorescence showed that the ERβ in the DRN of PMS anxiety rats was significantly decreased and TPH2 and SERT showed corresponding abnormal expression." (PMID 32219134, 2020). "This study is to investigate the effect of Paeonia lactiflora extract on PMS anxiety and on expression of estrogen receptor β (ERβ), tryptophan hydroxylase-2 (TPH2), and serotonin transporter (SERT) in the premenstrual syndrome (PMS) anxiety model rats." (PMID 32219134, 2020). "This was, however, dependent on the experience of MS during early life and Tph2+/- and Tph2+/+ mice of the MS group showed similar levels of anxiety." (PMID 31133792, 2019). "Mice with genetic deletion of TPH2 exhibited a complex phenotype, whereby elevated plus maze suggested lower level of anxiety, while forced swim test revealed increased immobility and the aggressive behavior was greatly increased in these knockout mice." (PMID 30377380, 2019). "Our data demonstrate that two models of inescapable stress, IS and cold swim, increase tph2 mRNA expression selectively in the anxiety-related dorsomedial DR (cDRD)." (PMID 29520369, 2018). "Depletion of brain 5-HT in Tph2 mutant mice resulted in reduced behavioural despair, reduced anxiety, marked aggression and lower habituation in novel environments, reminiscent of bipolar-associated manic behaviour." (PMID 30087403, 2018). "Our results revealed that the expression levels of the 5-HT-related synthesizing enzyme (tph2) and transporter (slc6a4) genes were significantly depleted in parallel to the occurrence of anxiety-like behaviors in LPS-induced offspring." (PMID 28650979, 2017). "We concluded that maternal immune activation induced by exposure to a low dose of LPS decreased cerebral 5-HT levels in parallel to the down-regulation of the tph2 and slc6a4 genes and in conjunction with anxiety-like behaviors in offspring." (PMID 28650979, 2017). "Our results indicated that the concentration of the cerebral 5-HT and gene expression of the tph2 and slc6a4 were decreased in conjunction with the appearance of anxiety-like behaviors in the adolescent and adult offspring of the LPS-induced groups." (PMID 28650979, 2017). "Together, these results indicate that excitation of tph2 serotonergic neurons influences avoidance of darkness, potentially by increasing anxiety." (PMID 26868164, 2016). "These TPH2 knock-in (KI) mice exhibit reduced serotonin synthesis by 80%, and increased depressive- or anxiety-like behaviors." (PMID 25964750, 2015). "Our results demonstrate that anxiety-like behavior in Tph2 mice is moderated by sex, stress, and genotype." (PMID 25716307, 2015). "From a behavioral perspective, TPH2-/- mice show intense compulsivity and impulsivity, social communication deficits and exaggerated aggression with decreased levels of anxiety-like behavior." (PMID 25706994, 2015). "Lastly, chronic corticosterone in the drinking water, which increases anxiety-like behavior in a social interaction task, open field task, and elevated plus maze, increases tryptophan hydroxylase 2 (TPH) mRNA in the DRD." (PMID 24065880, 2013).
Anxiety (continued). "Repeated administration of UCN 1 into the BLA has also been shown to induce serotonergic changes in the DR, including an increase in tph2 mRNA in specifically the DRVL that was correlated with increases in anxiety-like behavior." (PMID 24065880, 2013). "The light-dark and dark emergence tests of anxiety were used to test TPH2−/− weanling mice for anxiety-like behaviors as described in Materials and Methods S1." (PMID 23139830, 2012). "In several other studies, TPH2 KO rodents displayed phenotypic changes such as, for instance, high levels of aggressive behavior, autistic-like behavior traits and unexpectedly decreased anxiety-like behavior in comparison with WT controls." (PMID 40141402, 2025). "Furthermore, maternal separation during early life, which induces a chronic anxiety-like state throughout adulthood, increases tph2 mRNA expression in the cDRD in rats." (PMID 38705984, 2024). "However, it was reported that Tph2 null mutants (Tph2−/−) mice showed slightly reduced depression-like and anxiety-like behaviors, but significantly increased fear-conditioning responses." (PMID 36010683, 2022). "Thus, in this study, the reverse Tph2‐/‐phenotype refers to the examination of the animal phenotype (i.e., altered impulsivity, aggression, and anxiety) in humans." (PMID 33523602, 2021). "The mild depressive-like behavior was associated with unchanged TPH2-immunoreactivity in the dorsal raphe, thereby highlighting sex differences as evidenced by increased anxiety- and despair-like behaviors and reduced TPH2-immunoreactivity in neural ERβ knockout females." (PMID 32277160, 2020). "Specifically, we found that CEE and E2 increased TpH2 mRNA in distinct subregions of the DRN, and that these increases in TpH2 were associated with improved cognitive performance, decreased anxiety-like behaviors, and decreased depressive-like behaviors, in a region-specific manner." (PMID 28008302, 2016). "We demonstrated here that animals with higher TpH2 expression in the caudal DRN tended to exhibit decreased anxiety-like behaviors in two rodent tests of anxiety, the OFT and the EPM, suggesting that higher levels of TpH2 expression in the caudal DRN are associated with an anxiolytic profile." (PMID 28008302, 2016). "From a behavioral perspective, the TPH2-/- mouse shows intense compulsivity and impulsivity, autism-like social communication deficits and exaggerated aggression with decreased levels of anxiety." (PMID 25706994, 2015). "Indeed, the transcription factor PET-1 maintains Tph2 expression in 70% of CNS 5-HT neurons in adult mice to influence anxiety behavior." (PMID 26402365, 2015). "Our present findings clearly support this existing view and decreased calling after isolation in Tph2-/- mouse pups might be correlated with reduced anxiety-related behavior in adulthood." (PMID 25901271, 2015). "While male Tph2−/− showed reduced anxiety in the EPM and OF, Tph2−/− females exhibited increased anxiety, as reflected by novelty-induced locomotor suppression and increased stress-related autonomic reactivity in the OF but reduced anxiety in the EPM without an increase in locomotion." (PMID 25716307, 2015). "Interestingly, Tph2−/− mice showed reduced anxiety-like behavior in the EPM indicated by reduced time spent in the closed arms." (PMID 25716307, 2015). "In spite of the 50% decrease in Tph2 transcriptional activity, Tph2+/− mice only have a 10% reduction of brain 5-HT, which is insufficient to differentiate them from the Tph2+/+ ones on aggression and anxiety-like behaviors." (PMID 24782727, 2014). "Mosienko and colleagues also showed that TPH2−/− mice have decreased anxiety-like behavior." (PMID 23139830, 2012). "Thus, in the present study, we investigated the effects of a HFD treatment for 9 weeks on the gut microbiome, expression of tph2, htr1a and slc6a4 genes in the brainstem raphe nuclei, and anxiety-related defensive behavioral responses in adult male Wistar rats." (PMID 38705984, 2024).